LYSMD1 (LysM domain containing 1)
Synonyms: SB145; MGC35223; RP11-68I18.5
Tractability: PROTAC: its protein half-life has been measured.
Gene: Protein-coding gene on chromosome 1 (151,159,748 to 151,165,948, reverse strand). Ensembl gene ENSG00000163155.
Subcellular location (Human Protein Atlas): Nucleoplasm
Gene Ontology:
Molecular function: protein binding
Cellular component: nucleoplasm
Genetic constraint (gnomAD): Loss-of-function variants: 9 observed, 20.04 expected, observed/expected ratio (o/e) 0.45, 90% interval 0.27 to 0.78. The upper end of that interval is the gene's LOEUF score, 0.78, which puts it in group 3 of 6, group 1 being the genes least tolerant of losing a copy. Missense variants: 262 observed, 295.23 expected, observed/expected ratio (o/e) 0.89, 90% interval 0.8 to 0.98. Synonymous variants: 111 observed, 118.63 expected, observed/expected ratio (o/e) 0.94, 90% interval 0.8 to 1.1.
Homologues: Orthologues: chimpanzee LYSMD1 (99% identical), macaque LYSMD1 (96% identical), pig LYSMD1 (93% identical), rabbit LYSMD1 (89% identical), dog LYSMD1 (89% identical), guinea pig LYSMD1 (85% identical), mouse Lysmd1 (84% identical), tropical clawed frog lysmd1 (48% identical), zebrafish lysmd1 (45% identical), Caenorhabditis elegans lmd-1 (16% identical), Drosophila melanogaster CG17985 (15% identical). Paralogues in human: LYSMD2 (35% identical), LYSMD3 (19% identical), LYSMD4 (18% identical).
Diseases named in the same sentence as LYSMD1 in open-access papers:
LYSMD1 is named in the same sentence as 1 disease in open-access papers, as found by Europe PMC text mining. Sharing a sentence is not in itself a finding about the gene and the disease. The quoted sentences say what the papers report.
cancer (1 paper, 2023). A tumor composed of atypical neoplastic, often pleomorphic cells that invade other tissues. "Nevertheless, LYSMD1 was negatively correlated with anti-cancer immunity, which might contribute to cold TME and immunosuppression." (PMID 36873930, 2023).